EGR1 (early growth response 1)
Diseases named in the same sentence as EGR1 in open-access papers (continued):
Sharing a sentence is not in itself a finding about the gene and the disease.
cholestasis (7 papers, 2020 to 2025). Impairment of the bile flow caused by obstruction within the liver, or outside the liver in the bile duct system. "EGR1 has been identified as potential therapeutic target to inhibit the inflammation induced by cholestasis for cholestatic liver injury." (PMID 37152289, 2023). "During cholestasis, EGR1 regulates the production of inflammatory mediators, including cytokines and adhesion molecules, that promote the accumulation and activation of inflammatory cells, causing liver injuries." (PMID 32923184, 2020). "Additionally, research has demonstrated that EGR1 can inhibit cholestasis-induced hepatic inflammatory responses, highlighting its significant value in the treatment of liver injury." (PMID 40996711, 2025). "Egr1 is an early stress response gene, and its absence strongly attenuates inflammation in the BDL model of cholestasis." (PMID 39358604, 2024). "Online data mining suggested that cholestasis might upregulate ACER3 via transcription factors SP1, EGR1, and STAT3, which were determined as potential regulators of ACER3 expression and known to be activated by cholestasis." (PMID 40025008, 2025).
colitis (7 papers, 2021 to 2025). Inflammation of the colon. "Another study to show TNF-α induction of heparanase (during colitis-associated tumorigenesis) proposed that since TNF-α also induced upregulation of EGR1 that TNF-α induced heparanase expression via activation of EGR1, although this is yet to be confirmed." (PMID 34681753, 2021). "Furthermore, our results suggest that colitis-associated overexpression of Atf4 and Egr1 cannot be reversed by MM depletion and l-clodronate treatment." (PMID 38105266, 2023). "EGR1 transcription is reduced during colitis, resulting in downregulation of KLK1 in goblet cells, which impairs mucosal barrier integrity and reduces Lys‐des‐Arg9‐BK levels, leading to upregulation of B1R in ADAMDEC1+ fibroblasts." (PMID 40859429, 2025). "Taken together, EGR1 downregulation contributes to the inflammatory balance and gut barrier protective effects of ligustilide in colitis mice." (PMID 40904624, 2025). "High levels of Egr1 expression were observed in a mouse model of colitis induced by dextran sulfate sodium (DSS), as determined by immunohistochemical (IHC) staining." (PMID 38672136, 2024). "Finally, we utilized AAV-EGR1 to overexpress EGR1 in vivo and evaluate the potential role of EGR1 as an essential target for ligustilide in colitis mice." (PMID 40904624, 2025). "Additionally, the EGR1 overexpression (OE-EGR1) mouse model ascertained the fundamental role of EGR1 in ligustilide exerting protective effect against colitis." (PMID 40904624, 2025). "Finally, the in vivo experiment with EGR1 overexpression proved that EGR1 was essential for the protective effects of ligustilide on colitis mice." (PMID 40904624, 2025). "Moreover, in mice with dextran sulfate sodium salt (DSS)-induced colitis, diminished manifestation of Egr-1 and Foxp3 was discerned in colon tissue (P < 0.01 and P < 0.001)." (PMID 40235598, 2025). "Kyoto Encyclopedia of Genes and Genomes (KEGG) analysis indicated that EGR1 overexpression significantly affected multiple pathways, of which the TNF-α signaling pathway was closely connected with the macrophage inflammatory response in colitis." (PMID 40904624, 2025). "Given the significant impact of Egr-1 in CD4+ T cells for EAE and colitis treatment, it is plausible that Egr-1 could represent a potential curative target for various self-antigen reactive diseases, warranting further investigation into its clinical applications." (PMID 40235598, 2025).
lymphoma (7 papers, 2012 to 2025). A malignant (clonal) proliferation of B- lymphocytes or T- lymphocytes which involves the lymph nodes, bone marrow and/or extranodal sites. "In studies on lymphoma, EGR-1, an early growth response protein 1, is expressed by stromal cells within lymphoma tissues and inhibits the transcriptional activation of the MMP-9 gene in these stromal cells." (PMID 39712025, 2024). "JNK inhibition downregulates the early growth response gene-1 (Egr-1) protein and Egr-1 overexpression partially rescues lymphoma cell apoptosis." (PMID 31994958, 2020). "Of note, malignant cells isolated from such lymphomas become sensitive to OXPHOS inhibitors, suggesting that targeting OXPHOS and EGR1, either separately or in combination, may prove efficacious in patients with lymphomas overexpressing EGR1." (PMID 38638855, 2024). "A previous study reported that EGF-induced EGR1 expression could be involved in the down-regulation of matrix metallopeptidase 9 (MMP9) expression in lymphoma cells." (PMID 31635309, 2019). "EGR-1 activation by EGF inhibited MMP9 expression and lymphoma growth." (PMID 22461839, 2012). "Therefore, EGR1-mediated PDP1 activation increases intracellular ATP production, providing sufficient energy to enhance the proliferation and survival of ibrutinib-resistant lymphoma cells." (PMID 40746885, 2025).
Parkinson disease (7 papers, 2015 to 2024). A progressive degenerative disorder of the central nervous system characterized by loss of dopamine producing neurons in the substantia nigra and the presence of Lewy bodies in the substantia nigra and locus coeruleus. "EGR1 has also been implicated in the neuroprotection of motor function and dopaminergic neurons in Parkinson’s disease." (PMID 39840278, 2024). "Egr1 (early growth response 1) and Nfkb1 (nuclear factor-κb subunit 1) induce the transcription of pro-inflammatory cytokines, and EGR1 activation promotes neuroinflammation and degeneration in experimental Parkinson's disease." (PMID 35529318, 2022).
Sepsis (7 papers, 2018 to 2025). Sepsis is defined as life-threatening organ dysfunction caused by a dysregulated host response to infection. "Our study reports the mechanism of the association between rs653765 and the risk of sepsis progression and provides the EGR1/ADAM10 pathway involving the regulation of nosogenesis of sepsis based on the clinical genetic evidence." (PMID 31387910, 2019). "Interestingly, PLD1 mediates TNF-α regulation via MEK1 and ERK phosphorylation leading to reduced Egr1 expression after LPS-induced sepsis in PLD1 deficient mice." (PMID 30555342, 2018). "EGR1 is recognized as a pleiotropic inflammatory transactivator that appears to be a master regulator in a variety of proinflammatory pathological processes, which is closely associated with the pathogenic mechanism of inflammatory-related diseases, such as sepsis and cancer (51, –, 55)." (PMID 31387910, 2019). "The specific mechanisms included increases in the lactate level and histone H3 lysine 18 lactylation (H3K18la) induced by sepsis, which activated EGR1/HPSE signaling, promoting the degradation of the glycocalyx barrier." (PMID 39721014, 2025). "In vivo, silencing EGR1 alleviated sepsis‐induced degradation of the vascular endothelial glycocalyx and lung injury." (PMID 39721014, 2025). "Subgroup analysis found that the EGR1 expression level was significantly increased in severe sepsis compared with that in the septic shock group." (PMID 31387910, 2019). "The expression level of EGR1 in sepsis patients was evaluated to further characterize the clinical association between EGR1 and ADAM10." (PMID 31387910, 2019). "Here we show that patients with sepsis exhibited significantly higher EGR1 mRNA expression levels than the healthy controls." (PMID 31387910, 2019). "This evidence suggests the potential crucial role of EGR1 in regulating ADAM10 expression in sepsis patients." (PMID 31387910, 2019). "EGR1 silencing significantly attenuated sepsis‐induced pulmonary vascular permeability." (PMID 39721014, 2025). "Next, we investigated whether EGR1 silencing can attenuate sepsis‐induced glycocalyx degradation and ALI in vivo." (PMID 39721014, 2025). "However, only three genes (CD44, MMP9, and EGR1) were found to be significantly upregulated in the sepsis model, correlating with our bioinformatic results." (PMID 35205254, 2022). "In the present study, we confirmed that a functional variant acts as an important genetic factor that confers the progression of sepsis in a large sample size and in multiple centers and revealed that the variants modulate the EGR1/ADAM10 pathway and influence the severity of sepsis." (PMID 31387910, 2019). "Thus, our data suggest new insight into the novel mechanism of the EGR1/ADAM10 pathway in the regulation of sepsis progression." (PMID 31387910, 2019). "Consistently, our previous study showed that the ADAM10 mRNA expression levels in the sepsis group were significantly higher than in controls, underscoring the fact that EGR1 correlates well with ADAM10 expression in sepsis patients and potentially plays a crucial role in the progression of sepsis." (PMID 31387910, 2019). "Therefore, EGR1 can be a diagnostic marker for SLE and sepsis." (PMID 35205254, 2022). "In vivo, suppression of lactate production or genetic knockout of EGR1 mitigated glycocalyx degradation and ALI and improved survival outcomes in mice with polymicrobial sepsis." (PMID 39721014, 2025). "Based on degree centrality, 27 hub genes were selected, in which six genes (MMP9, CD44, EGR1, ACTN2, TNNT3, and PTGS2) were selected on the basis of a multi-network variable selection approach and validated in a well-established sepsis mice model." (PMID 35205254, 2022). "Only three genes (EGR1, MMP8, and cd44) were shown to be prevalent in the DEGs of sepsis, SLE, and CRS." (PMID 35205254, 2022).
Sepsis (continued). "The direct binding of the EGR1 to the ADAM10 promoter is modified, affecting the transcription and translation of the ADAM10 gene, resulting in enhanced inflammatory responses and ultimately stimulating the progression of sepsis in vitro and in vivo." (PMID 31387910, 2019). "In light of the crucial role of the EGR1/ADAM10 signaling pathway in the sample of sepsis patients and in vitro models that confirmed this, we evaluated whether EGR1 could serve as a therapeutic target for sepsis." (PMID 31387910, 2019).
endothelial dysfunction (6 papers, 2014 to 2024). In vascular diseases, endothelial dysfunction is a systemic pathological state of the endothelium (the inner lining of blood vessels) and can be broadly defined as an imbalance between vasodilating and vasoconstricting substances produced by (or acting on) the endothelium. "Increased miR-551b expression was shown to lead to endothelial dysfunction by upregulating Egr-1 expression." (PMID 37987363, 2023). "A large body of evidence illustrates Egr-1 as a key regulator of endothelial dysfunction in the context of atherogenesis." (PMID 32974343, 2020). "The induction of Egr1 leads to microglial activation and can contribute to endothelial dysfunction." (PMID 33981252, 2021). "In addition to HIF and Egr-1, the ALOX5 promoter region also contains binding sites for TGF-β and NF-κB, which are also implicated in the endothelial dysfunction and vascular remodeling in PH pathogenesis." (PMID 24906007, 2014).
Hepatic steatosis (6 papers, 2017 to 2025). Steatosis is a term used to denote lipid accumulation within hepatocytes. "Studies have shown the importance of EGR1 in maintaining the hepatic insulin response and claimed that the loss of EGR1 in hepatocytes leads to hepatic steatosis, which exacerbates the progression of non-alcoholic liver disease." (PMID 37405258, 2023). "EGR1 is a transcription factor that regulates the expression of numerous genes, including many important for liver health, including genes regulating fibrosis, inflammation and EtOH-induced hepatic steatosis." (PMID 41007411, 2025). "The report of Egr1 function in liver steatosis is somehow contradictory." (PMID 29607419, 2017). "In addition, whole-body Egr1−/− mice are protected from chronic ethanol-induced fatty liver due to the decreased expression and release of TNFα from macrophages." (PMID 29607419, 2017). "However, recent studies highlight that increasing Egr1 levels in the liver ameliorates diet-induced fatty liver disease." (PMID 29607419, 2017). "For example, the white pitaya (hylocereusundatus) juice attenuates diet-induced liver steatosis and improves insulin sensitivity in C57BL/6J mice, which is accompanied by an increase in hepatic Egr1 mRNA level." (PMID 29607419, 2017).
psoriasis (6 papers, 2013 to 2022). An autoimmune condition characterized by red, well-delineated plaques with silvery scales that are usually on the extensor surfaces and scalp. "A previous study showed that Egr-1 is significantly upregulated in the skin lesions of psoriasis patients and promotes TNF-α production." (PMID 35693817, 2022). "EGR1 overexpression has been identified in psoriasis and considered a gene involving in the control of benign keratinocyte hyperproloferation." (PMID 30613363, 2018). "An analogue of 1,25(OH)2D3, calcipotriol which a potent inhibitor of keratinocyte proliferation and used for treating the hyperproliferative skin disorder psoriasis was found to inhibit EGR-1 expression in cultured human keratinocyte." (PMID 23527013, 2013). "Early growth respons-1 (Egr-1) is upregulated in T2DM and psoriasis." (PMID 26966903, 2016).
rhabdomyosarcoma (6 papers, 2014 to 2022). A rare aggressive malignant mesenchymal neoplasm arising from skeletal muscle. "In rhabdomyosarcoma, EGR1 overexpression reduces cell proliferation, motility, and anchorage-independent growth." (PMID 35978028, 2022). "The function of EGR1 has not been fully characterized in rhabdomyosarcoma (RMS), a pediatric cancer derived from the muscle linage." (PMID 29719592, 2018).
sarcoma (6 papers, 2015 to 2025). A usually aggressive malignant neoplasm of the soft tissue or bone. "About 30% of TCGA tumors, including most sarcoma subtypes, had a positive ssGSEA score indicating that a significant number of EGR1-driven genes are upregulated." (PMID 40875449, 2025).
scleroderma (6 papers, 2009 to 2024). Scleroderma is a rare autoimmune connective tissue disorder characterized by abnormal hardening of the skin and, sometimes, other organs. "We showed previously that aberrant TGF-β signaling in scleroderma was associated with sustained up-regulation of Egr-1 expression in the lesional skin." (PMID 19888474, 2009). "Although the relationship of EGR-1 and PPARγ in the kidney has not been investigated yet, the PPARγ agonist rosiglitazone decreased skin fibrosis and EGR-1 levels in a mouse model of scleroderma." (PMID 31277592, 2019). "Bleomycin-induced scleroderma in the mouse was accompanied by increased Egr-1 nuclear expression in lesional fibroblasts." (PMID 21365018, 2011). "The expression of Egr-1 was markedly up-regulated in the fibrotic lesion in a mouse model of scleroderma, as well as in skin and lung biopsies from patients with scleroderma." (PMID 19888474, 2009). "We demonstrated that levels of Egr-1 were markedly elevated in mice with bleomycin-induced scleroderma." (PMID 19888474, 2009). "Also, Rosiglitazone-mediated PPARγ activation inhibits Egr-1 generation, leading to suppression of bleomycin-induced scleroderma and profibrotic responses." (PMID 33717177, 2021). "Indeed, Egr-1 expression was found to be elevated in lesional skin tissues from mice with bleomycin-induced scleroderma, as well as in skin and lung biopsies from patients with diffuse cutaneous SSc." (PMID 21931594, 2011). "The present results show that while Nab2 expression was highly elevated in scleroderma skin biopsies, in contrast to Egr-1, it was localized almost exclusively to the epidermis and epithelial cells lining dermal appendages, whereas dermal fibroblasts showed scant Nab2 expression." (PMID 19888474, 2009). "We have shown that Egr-1 expression was up-regulated in scleroderma skin biopsies." (PMID 19888474, 2009). "Moreover, the expression of Egr-1 was found to be enhanced in skin and lung biopsies from patients with scleroderma." (PMID 19888474, 2009). "The early growth response-1 (Egr-1) transcription factor mediates profibrotic TGF-β responses, and its expression is elevated in biopsies from patients with scleroderma." (PMID 19888474, 2009). "Additionally, EGR1 is aberrantly expressed in animal models such as transgenic mice expressing TGF-ß or IL-13 and human fibrotic diseases such as IPF and scleroderma." (PMID 39944354, 2024). "A subset of skin biopsies from patients with dcSSc, but not other forms of scleroderma, show evidence of robust Egr-1-dependent gene activation." (PMID 21931594, 2011). "While Nab2 expression was dramatically up-regulated in epithelial cells in scleroderma skin biopsies, consistent with activated TGF-β signaling in the fibrotic milieu, dermal fibroblasts from biopsies that were strongly immunopositive for Egr-1 and phospho-Smad2 showed a paucity of Nab2 expression." (PMID 19888474, 2009).
ZIKV infection (6 papers, 2017 to 2022). "Loss of function studies indicated that EGR1 at least partially regulates the expression of transcription factor KLF4 and inflammatory mediator TNF-α following ZIKV infection of astrocytes." (PMID 36338037, 2022). "EGR1 was slightly (~1.5-fold over mock), but significantly, upregulated in response to ZIKV infection." (PMID 35746681, 2022). "However, to date, the full functional significance of EGR1 in JEV or ZIKV infections has yet to be determined." (PMID 36338037, 2022). "In addition, the lack of a cytopathic effect could be due to the induction of the pro-survival genes during the ZIKV infection of hBMECs, including EGR1, ATF3, and BIRC3." (PMID 36557673, 2022). "In flavivirus infection, EGR1 was found to be commonly upregulated in TEM and TEMRA in both DENV and Zika virus infection." (PMID 34079535, 2021). "CXCL3, CXCL8, and PTGS2 were all slightly, but not significantly, induced following ZIKV infection, and the expression of all three inflammatory mediators was significantly decreased in the EGR1−/− infected cells as compared to the WT mock-infected cells." (PMID 35746681, 2022). "ATF3 transcription was slightly, but not significantly, upregulated following ZIKV infection in WT cells but transcription was significantly reduced in the EGR1 null-infected cells." (PMID 35746681, 2022). "Thus, it would be interesting to further explore the role of EGR1 in regulating PTGS2 and TNF-α expression following ZIKV infection." (PMID 35746681, 2022). "This study noted the induction of ATF3, EGR1, JUNB, IRF7, ISG15, HERC5/6, additional ISGs, chemokines CCL5 and CXCL10, prosurvival responses, and decreased proapoptotic genes, similar to gene induction levels we found to be induced by ZIKV infection of hBMECs (GEO GSE98889)." (PMID 28698279, 2017). "Genes associated with cell differentiation and proliferation, such as BUB1, DLGAP5, PBK and CEP55 (Cluster 3) were upregulated during DENV infection but not ZIKV, while EGR1, HBEGF and MAFB (Cluster 4), were up-regulated at d17 POS during ZIKV infection." (PMID 30596671, 2018).
amnesia (5 papers, 2012 to 2025). Pathologic partial or complete loss of the ability to recall past experiences ( AMNESIA, RETROGRADE) or to form new memories ( AMNESIA, ANTEROGRADE). "Therefore, the promoted gene and protein expression of Arc, Egr1, Homer1 and Narp by EA treatment also indicated the therapeutic effect of EA on scopolamine-induced amnesia." (PMID 33183243, 2020).